STAT3 (signal transducer and activator of transcription 3)
Diseases named in the same sentence as STAT3 in open-access papers (continued):
Sharing a sentence is not in itself a finding about the gene and the disease.
tumor (continued). "Elevated levels of IL8 have been linked to poor prognosis in patients suffering from HNSCC by activating signalling downstream RAS/MAPK and STAT3 (signal transducer and activator of transcription 3), and release of MCP1 supports the recruitment of monocytes and tumour-associated macrophages (TAM)." (PMID 37460712, 2023). "Furthermore, miR-101 inhibited T-ALL tumor development by targeting CXCLI2/CXCR7/STAT3 signaling pathway activation." (PMID 37497001, 2023). "Furthermore, mechanistic analysis of suppression of miR-21 and STAT3 co-expression by employing STAT3 inhibitor revealed an upsurge in tumor suppressive phosphatase and tissue inhibitor of metalloproteinase expression." (PMID 38170015, 2023). "Signal transducer and activator of transcription 3 (STAT3) is a crucial signaling mediator promoting immunosuppression in tumor-associated immune cells, as well as proliferation, survival, and angiogenesis in tumor cells." (PMID 37945711, 2023). "In addition, the JAK2/STAT3 signaling pathway can regulate tumor angiogenesis through modulation of several angiogenesis-related genes." (PMID 36890596, 2023). "While the exact molecular mechanism of action for SC144-mediated polarization of macrophages and ICD induction is beyond the scope of this work, prior literature suggests that the IL-6/gp130/STAT3 axis plays a crucial role in tumor progression and immunosuppression." (PMID 37553327, 2023). "The IL6/JAK2/STAT3 signaling axis is best studied in the context of tumor metastasis and tumor pathology since it induces epithelial–mesenchymal transition (EMT), resulting in tumor metastasis by promoting the expression of EMT-inducing transcription factors, such as Snail, ZEB1, JunB, and Twist1." (PMID 38203502, 2023). "Additionally, LYN-kinase and other Src kinase families were proven to be involved in activation of STAT3-mediated and NF-κB-mediated tumor progression." (PMID 37416766, 2023). "Additionally, Angelica polysaccharide was found to suppress tumor metastasis by inhibiting Stat3 phosphorylation in macrophages and preventing their polarization toward the M2 phenotype." (PMID 38035069, 2023). "It fulfills its role in tumor metastasis by promoting STAT3 activation and cell migration." (PMID 37409245, 2023). "Within panCK‐positive tissues high STAT3 within the stroma was associated with increased expression of VEGFA (p = 0.0110), which has been shown to be independently prognostic in TNBC and associated with more aggressive tumour phenotypes." (PMID 37199043, 2023). "Targeting STAT3 may reduce tumor cell-intrinsic proliferation, increase tumor-infiltrating immune cell anti-tumor activity, and improve TME immune suppression." (PMID 37799727, 2023). "Interestingly, HSP mediated immune suppression in tumor derived exosomes has been shown to operate in a STAT3 dependent manner." (PMID 36672227, 2023). "Moreover, these core genes (Pik3r1, Akt1, Myc, Egfr, Hif1a, Vegfr, Jun, and Stat3) are closely related to the tumor immune microenvironment, exclusively T cell immune function." (PMID 37799727, 2023). "Moreover, western blot analysis of proteins extracted from excised tumor revealed modest but discernable reductions in STAT3 p-Y705 expression compared to controls, as well as an increase in Caspase-3 cleavage, PARP cleavage and γH2A.X expression." (PMID 37126127, 2023). "Furthermore, persistently activated STAT3 can promote a pro-oncogenic inflammatory environment and subvert anti-tumor immunity." (PMID 37762241, 2023). "For example, NFs were induced by HPV-negative oropharyngeal cells to release hepatocyte growth factor (HGF) and IL-6, which might encourage tumor cell formation by activating c-met and STAT3." (PMID 37055382, 2023). "STAT3 had been found to be over-activated and played a tumor-promoting role in a variety of human cancers because STAT3 could act as a transcription factor to promote the expression of cyclin-B1, cyclin-D1, MMP2, MMP9 and other pro-tumor proteins." (PMID 37161425, 2023).
tumor (continued). "Res and TMZ exert the anti-tumor effects mainly by inhibiting STAT3 signaling, and inhibition of STAT3 signaling might be related to upregulation of PIAS3, SHP1, SHP2, and SOCS3." (PMID 37298405, 2023). "On the other hand, B cells with STAT3 activity were revealed to be associated with tumour angiogenesis, thus determining that B cells with STAT3 activity can mediate tumour progression and may be utilized as potential treatment targets for malignant tumour." (PMID 37815881, 2023). "Stat3 exhibits pro-tumor effects in many cancers, whose target genes include NF-κB." (PMID 37901456, 2023). "Similarly, mice lacking S1P lyase at the intestinal level exhibited greater disease activity of colitis-associated cancer, cytokine level increase, S1P accumulation, tumor formation, colon shortening and STAT3 activation." (PMID 38203299, 2023). "The activation of ROS, Src, and STAT3 was also detected in tumor biopsies from HNSCC patients." (PMID 36446524, 2023). "This is due to the induction of phosphorylation in tumor cells by cytotoxic T-cell immunotherapy, which specifically targets the transcription factors signal transducer and activator of transcription 3 (STAT3) and early growth response-1 (EGR-1) and subsequently promotes the formation of CIC." (PMID 37637068, 2023). "By inhibiting STAT3 phosphorylation and nuclear translocation, cinobufagin could transcriptionally regulate STAT3 activity, which could inhibit the occurrence and development of tumor." (PMID 37928418, 2023). "Furthermore, BBR suppresses migration and invasion of tumor cells via the IL-6/JAK2/STAT3 signaling pathway and inhibiting MMP-9 protein levels." (PMID 37371856, 2023). "Indeed, literature data suggested that the STAT3 pathway is activated upon tumour cell stimulation with IL-6." (PMID 36979673, 2023). "EZH2 can also methylate STAT3 in breast cancer cells, which was necessary for tumor growth." (PMID 37664059, 2023). "Additionally, elevated levels of aldehyde dehydrogenase (ALDH) in endometrial cancer can promote CSC traits through IL-6/JAK1/STAT3-mediate pathways, thereby blocking these pathways declined tumor growth and progression." (PMID 38017510, 2023). "To examine whether STAT3 KD inhibits tumor growth in vivo and sensitizes MB tumors to cisplatin treatment, we first utilized a subcutaneous tumor xenograft model with HD-shSTAT3 and ONS-shSTAT3 cells." (PMID 37190167, 2023). "As a result, our experiments indicated that inhibition of YAP could affect TME and tumor proliferation at least through the STAT3/VEGF/VEGFR‐2 axis." (PMID 37329188, 2023). "Importantly, we show that STAT3 KD or inhibition with WP1066 attenuates MB tumor growth in a subcutaneous xenograft and in an orthotopic MB model and sensitizes MB tumor to cisplatin chemotherapy." (PMID 37190167, 2023). "It is well known that aberrant overexpression of IL-6 drives the formation of the tumor microenvironment, and OS tumor cells produce large amounts of soluble IL-6, accompanied by increased phosphorylation of STAT3, and exhibit strong chemotaxis to those factors." (PMID 37404767, 2023). "TCAF2 is highly expressed in tumor pericytes (TPCs) derived from patients with colorectal cancer liver metastasis (CRCLM), which induces the secretion of Wnt5a through inhibiting TRPM8 channel and activates the STAT3 phosphorylation in tumor cells, thus facilitating CRCLM." (PMID 37635201, 2023). "STAT3 activation in ECs is involved in tumor cell adhesion to ECs and metastasis." (PMID 37124539, 2023). "IL-6 leads to STAT3 activation, playing a pivotal role in tumor initiation and progression." (PMID 37047623, 2023). "In addition, staining images showed that the tumor margins were smoother in the STAT3- and SRF-knockdown groups." (PMID 37558923, 2023). "In addition, the interaction between lncRNA ATB and IL-11 mRNA triggers the STAT3 signal, which can promote tumour cell colonization in organs." (PMID 36447000, 2023).
tumor (continued). "STAT3 is a key regulator of cancer-related inflammation and tumor progression." (PMID 37480054, 2023). "The dysregulated function of STAT3 has been observed in many cell lines and tumor tissues." (PMID 37308913, 2023). "Moreover, inhibition of CMTR1 using siRNA reduced RNAPII binding to the STAT3 TSS and subsequently suppressed STAT3 expression and activation, providing important insights into the immune evasion of tumor cells in CRC." (PMID 37024465, 2023). "Next, we randomly treated an orthotopic PDAC mouse with vehicle or Stattic at 3.75 mg/kg/day to investigate whether STAT3 suppression modulates tumor progression and the immune microenvironment in vivo." (PMID 38001876, 2023). "Furthermore, it has been reported that tumor-associated macrophages promote RCC epithelial-mesenchymal transition, migration, and invasion via activating IL-6/STAT3 signaling." (PMID 37927783, 2023). "In mice, a tumor formed of HCT-116 cells after silencing STAT3 grew slower than the control group." (PMID 38067351, 2023). "This increased tumor burden in TLR2−/− mice was further explained by the overactivation of signal transducer and activator of transcription 3 (STAT3) in epithelial cells and the elevated expression of tumor-promoting cytokines, such as IL-6, IL-17A and TNF-α in the gut mucosa." (PMID 37519301, 2023). "In addition, recent research has shown that the signal transmitter and activator of transcription 3 (STAT3) is one of the genes that regulates cell proliferation and anti-apoptosis in various tumor cells." (PMID 37144620, 2023). "Moreover, CAF, which is a significant source of CCL2, can also activate the STAT3 signaling pathway to increase MDSCs recruitment and promote tumor progression." (PMID 37007004, 2023). "Furthermore, H2S can exert an anti‐angiogenic effect by inactivating Wnt/β‐catenin signalling or blocking the STAT3 pathway in tumours." (PMID 36478328, 2023). "Our study also demonstrates a potential of TMEM25 for targeted therapy of TNBC, and suggests that clinical mutations of TMEM25 identified in other types of cancer may be able to trigger monomeric-EGFR/STAT3 signaling to promote tumor progression as well." (PMID 37095176, 2023). "Furthermore, many efforts have been made to develop approaches to effectively inhibit STAT3 signaling activation in the tumor microenvironment." (PMID 37686472, 2023). "A tumor epithelial gp130 expression may indicate an activation of the IL-6/gp130/STAT3 pathway, which acts as a tumorigenic factor in PDAC." (PMID 36495330, 2023). "The finding that URB597 reduced the phosphorylation levels of AKT and STAT3 suggests that it may act on multiple signaling pathways that coexist in the complex tumor environment, thus exerting a crucial and broad role in weakening pro-malignant signals." (PMID 38139209, 2023). "used miRNA microarrays to identify miRNAs secreted by tumor exosomes; two of them, miR-9 and miR-181a, were shown to target protein inhibitors of activated STAT3 (PIAS3) and cytokine signaling protein 3 (SOCS3), respectively, therefore activating the JAK/STAT signaling cascade." (PMID 37465670, 2023). "It was shown that, in HNSCC, these cells produce IL-6, which regulates OPN expression through STAT3 activation, which may promote tumor proliferation." (PMID 38003931, 2023). "Similarly, our study showed that BBR effectively increased Akkermansia abundance and inhibited the L-6/STAT3 pathway in AOM/DSS mice fed with HFD, thus indicating a potential mechanism underlying BBR's prevention of tumor progression." (PMID 37151876, 2023). "Moreover, the expression of both JWA and NEDD4L was increased; however, EGFR, p-EGFR, p-AKT, and p-STAT3 expression levels were reduced in JAC4-treated tumor tissues compared to those in the control group." (PMID 37240137, 2023). "IL-6 promotes the activation of the STAT3 pathway, thereby promoting tumor cell proliferation." (PMID 38136358, 2023).
tumor (continued). "Moreover, another study found that inhibiting the activation of STAT3 in COL1+ fibroblasts can reduce tumor growth, while the activation of STAT3 can accelerate the progression of CAC." (PMID 37875976, 2023). "Many pro-inflammatory exogenic factors may promote neoplasm development through the nuclear factor-κB (NF-κB) and STAT3 signaling pathways." (PMID 36676131, 2023). "STAT3 is constitutively expressed in both immune and malignant cells and is an important mediator of the immunosuppressive inflammatory response in the tumor microenvironment and the tumor immune escape process." (PMID 36978108, 2023). "Within the tumor microenvironment, cancer cell interactions with adipocytes and macrophages promote cancer progression through a variety of mechanisms involving oxidative stress, IL-6, IL-1β, STAT3, ERK and CLS." (PMID 36670988, 2023). "It is possible that the cell–cell adhesion may be weak or defective at the tumor boundary, which leads to activation of Rac1 and then promotes cell migration through the ROS–Src–STAT3–vimentin signaling cascade, as proposed in this study." (PMID 36446524, 2023). "Additionally, STAT3 helps tumor cells to escape immune cycle by promoting transforming growth factor-β (TGF-β), VEGF, MDSC and suppressing NK cell function." (PMID 36675114, 2023). "The involvement of CKLF1 in tumor development may be related to its role in mediating the IL-6/JAK/STAT3 pathway." (PMID 36865551, 2023). "However, previous studies have found constitutive activation of STAT3 in various tumor cell lines and human tumor tissues, and STAT3 activation is considered a marker of poor tumor prognosis." (PMID 37946196, 2023). "Changes in STAT3 expression are accompanied by abnormal autophagy, which may affect each other during tumor development." (PMID 36937841, 2023). "mTOR-mediated control of STAT3 and NF-κB activities promotes an Immune-suppressive microglial phenotype that impedes the proliferation, infiltration, and immunological responses of effector T cells, thus facilitating tumor immune escape and growth." (PMID 37700840, 2023). "An interesting study has demonstrated that Stat3 induces expression of IL-23, which is mainly secreted by macrophages in the tumor microenvironment via transcriptional activation of the IL-23/p19 gene and through NF-κB/p65 activation, promoting tumor development." (PMID 37685766, 2023). "Sorcin exert its oncogenic effect by regulating key molecules such as VEGFs, MMPs, NF-κB, ERK1/ 2, CTSZ, Akt, STAT3, caspases involved in carcinogenesis and invasion of tumor cells and modulating signaling pathways including ERK, MAPK/ERK, and PI3K/Akt in various cancers." (PMID 37142981, 2023). "Within the tumour microenvironment and in the periphery, IL-6 promotes differentiation of myeloid precursors into MDSCs and reinforces their suppressive function by promoting and maintaining STAT3 phosphorylation." (PMID 36161514, 2023). "To determine whether this was also the case in the cancer cells of LUAD tumor tissues, we further examined p-STAT3 expression in the cancer cells of LUAD tumor tissue samples and associated them with the expression level of KDF1." (PMID 38137415, 2023). "Furthermore, the inhibitory effects of nuciferine on malignant behaviors and tumor growth in OSCC were shown to be attributed to the suppression of the STAT3 signaling pathway." (PMID 37833979, 2023). "We found differences in STAT3 expression between tumor and normal tissues." (PMID 37724127, 2023). "Furthermore, DSCC1 suppresses ER stress and promotes LUAD progress via interacting with HSP90AB1 and activating STAT3, and DSCC1 inhibits tumor immune infiltration via regulating HSP90AB1/STAT3/PD-L1 axis." (PMID 37742009, 2023). "The treatment induced tumor growth arrest and reduced STAT3 and ERK1/2 signaling." (PMID 38193080, 2023).
tumor (continued). "STAT3 hyperactivation could promote tumor cell proliferation, survival, angiogenesis, invasiveness, and metastasis and is often associated with poor patient outcomes." (PMID 37365152, 2023). "STAT3 is located at the intersection of multiple oncogenic signaling pathways, which can facilitate the growth, proliferation, progression and metastasis of tumor cells through multiple channels." (PMID 37450039, 2023). "To test whether the antitumor activity of the STAT3 inhibitor depended on CD146 expression on macrophages, we then treated tumor-bearing M-WT or KO mice with a STAT3 inhibitor." (PMID 37308559, 2023). "It has been suggested that BACE1 could alter cancer progression by changing the tumor microenvironment, activating STAT3 signaling via IL-6R, and subsequently maintaining tumor-promoting macrophages." (PMID 37511924, 2023). "When activated, STAT3 promotes tumor development and progression." (PMID 36852795, 2023). "Through a non-canonical NF-κB activation, this could cause IL6 expression to increase and then to up-regulate the STAT3-dependent signaling, ultimately leading to cancer cell survival and silencing of tumor-related inflammatory response." (PMID 37120444, 2023). "Furthermore, the IL-6R-neutralizing antibody inhibited STAT3 activation induced by MpMDCS stimulation in SBC-3 cells, suggesting that MpMDCS also enhances tumor proliferation via STAT3 activation induced by the IL-6/IL-6R signaling pathway." (PMID 36961655, 2023). "In particular, it has been known that CGRP may promote tumor growth via activation of extracellular signal-regulated kinases (ERKs)/Signal transducer and activator of transcription 3 (STAT3) signaling in cancer cells." (PMID 36737827, 2023). "In preclinical mouse models, a STAT3 inhibitor could prevent tumor immunosuppression and synergize with ICIs to improve antitumor responses." (PMID 37308559, 2023). "Recent studies, using the xenograft mouse model of OS, demonstrated that tumor extracellular vesicle-educated MSCs may promote osteosarcoma progression through IL-6 production and lung metastasis through STAT3 activation in tumor cells." (PMID 37892917, 2023). "Tumor-derived suppressive factors binding to corresponding receptors leads to continuous activation of STAT3, which then upregulates expression of STAT3-related genes and produces proteins (survivin and cyclin) and matrix metalloproteinase-9 (MMP-9) that promote MDSCs expansion." (PMID 37006306, 2023). "In addition, STAT3 activation induces tumor formation and poor prognosis of HCC via upregulation of the CD133 expression by directly interacting with the CD133 promoter." (PMID 37749450, 2023). "Both NF-κB and STAT3 are crucial in inflammation and tumor growth." (PMID 37818040, 2023). "MSCs can secrete IL‐6 in OS cells and promote their migration and invasiveness through the production of phosphorylated STAT3, suggesting that MSCs in the normal bone tissue surrounding the OS tissue can undergo OS metastasis and inhibit apoptosis of tumor cells through the STAT3 pathway." (PMID 37441462, 2023). "By downregulating the activation and nuclear translocation of STAT3, PA may inhibit tumor cell proliferation, metastasis, and promote antitumor immune responses." (PMID 37637038, 2023). "However, in human tumor cells, abnormal activation of the JAK/STAT3 signaling pathway occurs frequently, affecting the survival and proliferation of tumor cells, and is closely related to the poor prognosis of tumor treatment." (PMID 37781397, 2023). "STAT3 signaling is known to be altered by tissue stiffness, especially within the tumor context." (PMID 37640930, 2023). "Furthermore, we evaluated NF-κB and STAT3 in tumor xenograft models where MTDH remained depleted after 10 weeks." (PMID 36902125, 2023).